STK11 (serine/threonine kinase 11)
Diseases named in the same sentence as STK11 in open-access papers (continued):
Sharing a sentence is not in itself a finding about the gene and the disease.
hamartoma (15 papers, 1999 to 2025). A benign and excessive tumor-like growth of mature cells and normal tissues which grow in a disorganized pattern. "Somatic loss‐of‐function (LOF) mutations in STK11 occur in sporadic cancers 10, and mice with heterozygous LOF mutations of STK11 develop gastrointestinal hamartomas that mimicked the PJS phenotype." (PMID 30548122, 2019). "Loss of the C-terminal domain of STK11 leads to the loss of cell polarity and hamartoma formation as a result of inappropriate overgrowth of differentiated cells." (PMID 26607058, 2015). "These hamartomas were increasingly 18F-deoxyglucose-PET avid, suggesting that Stk11/LKB1 loss increases tumor cell uptake of glucose." (PMID 39113608, 2024). "On the other hand, Peutz–Jeghers syndrome is an autosomal dominant CRC predisposition syndrome also related to hamartomas and is mainly caused by germline mutations in the TSG STK11." (PMID 30871259, 2019). "Some neoplasms develop from hamartomas; however, as LKB1/STK11 has a role in a number of pathways involved in control of cell growth, it is likely that some mutations may confer an increased cancer risk through alternative mechanisms." (PMID 12865922, 2003).
juvenile polyposis syndrome (14 papers, 2013 to 2024). Juvenile gastrointestinal polyposis (JIP) is a rare condition characterized by the presence of juvenile hamartomatous polyps in the gastrointestinal (GI) tract. "Hereditary hamartomatous syndromes include Peutz–Jeghers syndrome (PJS, with mutations in LKB1/STK11), PTEN-hamartoma tumor syndrome (PHTS, with mutations in PTEN), and juvenile polyposis syndrome (JPS, with mutations in BMPR1A or SMAD4)." (PMID 38672634, 2024). "These include APC for familial adenomatous polyposis (FAP); BMPR1A and SMAD4 for Juvenile Polyposis Syndrome (JPS); MUTYH for MUTYH-associated polyposis; PTEN for PTEN tumor/hamartoma syndrome (or Cowden syndrome/Bannayan–Riley–Ruvalcaba syndrome); and STK11 for Peutz–Jeghers syndrome." (PMID 37965459, 2023). "Syndromes and corresponding genes include: SMAD4 (DPC4) and BMPR1A for juvenile polyposis (JPS), STK11 for Peutz–Jeghers (PJS) and PTEN and AKT1 for PTEN hamartomatous syndromes (PHS)." (PMID 36011318, 2022).
gastrointestinal polyp (13 papers, 2008 to 2025). A polypoid tumor that arises from any part of the gastrointestinal tract and protrudes into the lumen. "Patients who inherit a germline mutation in a single allele of the STK11 gene that encodes LKB1 develop a syndrome of gastrointestinal polyps; malignant tumors of the gastrointestinal tract and other tissues; and skin pigmentation." (PMID 22348111, 2012). "Furthermore, the loss of LKB1 expression due to a single allele mutation in STK11 in T cells leads to the formation of gastrointestinal polyps in mice due to the inflammatory cytokines from the mutated T cells." (PMID 40647497, 2025). "The potential relationship between truncating mutations of STK11 and severe complications discovered in this study may help PJS patients improve the quality of life by monitoring the development of GI polyps at an earlier age or at shorter intervals." (PMID 27821076, 2016).
hereditary pancreatitis (13 papers, 2014 to 2025). "The study demonstrated a diagnostic-yield for FPC (3%), PRSS1/SPINK1 (hereditary pancreatitis; 4%), CDKN2A (FM) (5%), BRCA1/2 and PALB2 (HBOC) (6.3%), and STK11/LKB1 (Peutz–Jeghers syndrome; PJS; 12.2%)." (PMID 38619782, 2024). "This study also calculated the NNS for specific HRI groups, with a NNS of 250 for a PV in BRCA genes, 130 for PRSS1/SPINK1 (hereditary pancreatitis), 71 for STK11/LKB (PJS) and 51 for a PV in the CDKN2A gene." (PMID 38619782, 2024). "In addition, it is known that the mutation in CDKN2A (also known as P16) is correlated with familial atypical mole melanoma syndrome (FAMM); in STK11 (also known as LKB1), is correlated with Peutz–Jeghers syndrome; and in PRSS1 and SPINK1, correlated with hereditary pancreatitis." (PMID 36672301, 2023).
cyst (12 papers, 2008 to 2022). A sac-like closed membranous structure that may be empty or contain fluid or amorphous material. "Because STK11-SNP was initially identified in members of the MSF who had tumor or cyst-related comorbidities, it was possible that this SNP is associated with those comorbidities, and not with MS." (PMID 25694554, 2015). "Interestingly, LKB1 (STK11) was shown to be part of a ciliary module comprising NPHP1, NEK7, ANKS3 and polycystin-1 that regulates cilia-controlled secretion of CCL2, a chemokine that promotes macrophage recruitment and consequent cyst growth and interstitial inflammation." (PMID 34055783, 2021).
bladder cancer (11 papers, 2007 to 2025). "Remarkably, among the key pathway nodes deregulated in bladder cancer, the LKB1/STK11-TSC-mTOR node was among the most commonly deregulated." (PMID 33477536, 2021).
metastatic disease (11 papers, 2015 to 2025). "Mutations in both TSC2 and STK11 were found exclusively in metastatic samples and are possibly associated with the development of metastatic disease or resistance to therapy." (PMID 32811538, 2020). "A patient with a PD-L1-negative, TMB-low, KEAP1/STK11 co-mutated metastatic non-small cell lung cancer (NSCLC) experienced a multisite radiological progression at 3 months after initiation of chemoimmunotherapy as first-line treatment for metastatic disease." (PMID 39170614, 2024). "KRAS/LKB1 (STK11) NSCLC metastatic tumors are intrinsically resistant to anti-PD-1 or PD-L1 immunotherapy." (PMID 35210547, 2022). "Patients with single or co-occurring STK11 and KEAP1 mutations had similar distributions in sex and primary versus metastatic tumor status compared with the mutation-negative group." (PMID 40427178, 2025).
polyposis (11 papers, 2012 to 2023). "All these facts make the p.Q82* of the NTHL1 gene screening reasonable in polyposis patients (especially in an unusual disease course), with APC, MUTYH, STK11, BMPR1A, and SMAD4 mutations excluded." (PMID 37834005, 2023). "STK11 (+/−) mice in previous studies were found to develop gastrointestinal hamartomatous polyposis, suggesting that haploinsufficiency of STK11 is a mechanism of PJS." (PMID 27821076, 2016). "Our ultimate goal is to enable an appropriate approach to prophylactic strategies in Polish families with polyposis, especially in those patients whose APC, MUTYH, STK11, BMPR1A, and SMAD4 gene testing showed no abnormalities." (PMID 37834005, 2023).
breast tumors (10 papers, 2013 to 2025). "For STK11, rs12488 was associated with the expression levels of C19orf24 in both breast mammary tissue and breast tumors." (PMID 35333900, 2022). "In the present study, we found that CD11b+Ly6C−Ly6G+ PMN-MDSCs were significantly increased in the peripheral blood of mice-bearing Stk11-KO breast tumors, and slightly expanded locally within the tumor microenvironment." (PMID 41051525, 2025). "In an orthotopic mouse breast tumor model, Stk11-KO cancer cells formed larger tumors than their parental counterparts, and circulating PMN-MDSCs were also expanded in mice-bearing Stk11-KO tumors." (PMID 41051525, 2025). "We observed a different pattern in breast tumors that metastasize to lung and harbor a mutation in KEAP1, KRAS, STK11, or EGFR." (PMID 32374727, 2020). "In contrast, deletion of STK11 in MYC-driven breast tumor models significantly reduced the latency period for tumor development." (PMID 24280377, 2013).
hereditary breast ovarian cancer syndrome (10 papers, 2014 to 2025). An autosomal dominant inherited syndrome caused by mutations in the BRCA1 or BRCA2 genes.
pancreatic ductal adenocarcinoma (9 papers, 2010 to 2025). An infiltrating adenocarcinoma that arises from the epithelial cells of the pancreas. "Notably, our findings revealed a significant positive correlation of PEBP1/STK11 co-expression and OS in pancreatic ductal adenocarcinoma (PAAD) exclusively, suggesting a potentially distinct role of these genes in PAAD progression and survival probability." (PMID 40806276, 2025).
esophageal squamous cell carcinoma (8 papers, 2019 to 2025). Esophageal squamous cell carcinoma (ESCC) is a type of esophageal carcinoma (EC) that can affect any part of the esophagus, but is usually located in the upper or middle third. "It is reported that STK11-activated autophagy enhances resistance to the combination of trametinib and radiation in KRAS-mutant NSCLC and promotes esophageal squamous cell carcinoma cell survival after radiation." (PMID 34434896, 2021).
lymph node metastasis (8 papers, 2012 to 2025). "STK11, on the other hand, functions as a tumor suppressor gene, and its reduced expression has been linked to higher histological grade, lymph node metastasis, and worse survival outcomes." (PMID 41300329, 2025). "Other factors like FAT3, APC, PTPRD (P = 0.01), lymph-node metastasis, EPHA3, TERT, and STK11 (P = 0.05) that have been found to be related to TMB distribution." (PMID 33996530, 2020).
lymphoma (8 papers, 2012 to 2024). A malignant (clonal) proliferation of B- lymphocytes or T- lymphocytes which involves the lymph nodes, bone marrow and/or extranodal sites. "It should be highlighted that MET, KDR (VEGFR) STK11 and BRAF are all upstream signaling components in the MAPK pathway and aberrant MAPK signaling is a known oncogenic mechanism in lymphoma." (PMID 29854308, 2018). "There are also data suggesting the contribution of serine/threonine kinase 11 (LKB1), a tumor suppressor kinase which negatively regulates mTORC1 activity, in lymphoma pathogenesis in animal models." (PMID 21822434, 2012).
renal fibrosis (8 papers, 2019 to 2025). A final common manifestation of a wide variety of chronic kidney diseases characterized by glomerulosclerosis and tubulointerstitial fibrosis. "Prior research has demonstrated that kidney-specific STK11 deletion mutations can exacerbate renal fibrosis by disrupting cellular metabolic pathways." (PMID 40676516, 2025).
steatosis (8 papers, 2012 to 2025). Increased lipid within the cytoplasm of cells. "This latter strain is not widely available, and its genetic contribution might account for the fasting steatosis at 11 dpf seen in wild-type siblings of serine/threonine kinase 11 (stk11)." (PMID 22678663, 2012).
cholangiocarcinoma (7 papers, 2015 to 2025). A carcinoma that arises from the intrahepatic biliary tree (intrahepatic cholangiocarcinoma) or from the junction, or adjacent to the junction, of the right and left hepatic ducts (hilar cholangiocarcinoma). "Knockdown of STK11 in cholangiocarcinoma cells activates Wnt/β-catenin signaling, thereby enhancing cell growth, migration, and invasion." (PMID 41051525, 2025). "LKB1 (also known as serine-threonine kinase 11, STK11) is a tumor suppressor, which is mutated in various cancers including cholangiocarcinomas." (PMID 26160843, 2015).
endometrial tumor (7 papers, 2016 to 2024). "Genes with co-alterations notably enriched in KRASm subsets included STK11 in non-Sq NSCLC, PIK3CA and APC in CRC, and ARID1A, PTEN, and PIK3CA in endometrial tumors." (PMID 36494601, 2022).
head and neck cancer (7 papers, 2013 to 2025). A primary or metastatic malignant neoplasm affecting the head and neck. "Loss of STK11 is associated with metastasis in head and neck cancer." (PMID 23718828, 2013). "In Head and Neck Cancer, it is unclear what mechanism is involved in decreasing STK11 levels." (PMID 32911741, 2020).
ovarian tumors (7 papers, 1999 to 2025). "In the case of PJS with a LEGH-like ovarian tumor, a heterozygous deletion mutation in STK11 was identified, further supporting the significance of STK11 variants in the proliferation of pyloric gland-type mucous epithelia across various anatomical sites." (PMID 39895895, 2025). "Moreover, the identification of STK11 variant in ovarian tumors is not specific to SCTAT, since it could be associated with Sertoli cell tumors of the ovary or STK11 adnexal tumors." (PMID 38136408, 2023).
Cachexia (6 papers, 2020 to 2026). Severe weight loss, wasting of muscle, loss of appetite, and general debility related to a chronic disease. "Collectively, these findings implicate tumor-derived GDF15 as a key mediator and therapeutic target in STK11/LKB1-mutant NSCLC-associated cachexia." (PMID 41617691, 2026). "We next depicted the tumor lines with STK11/LKB1 variants in our primary human NSCLC cachexia screen as a function of the relative fat and lean mass loss they promoted in immunodeficient mice." (PMID 37092555, 2023). "Loss of human or murine tumor STK11/LKB1 function led to cachexia-associated adipose and lean mass loss, resulting in significant weight loss in immunodeficient and immunocompetent mice, respectively." (PMID 37092555, 2023). "With their generalized importance in supporting cell transformation, STK11/LKB1 mutations can represent a surrogate in identifying patients who will develop cachexia across multiple primary cancers." (PMID 37092555, 2023). "Furthermore, our studies demonstrated that STK11/LKB1 alterations promote local and systemic increases in pro-inflammatory cytokines associated with signaling changes in host tissues that resemble the ones previously observed with cachexia-associated wasting." (PMID 37092555, 2023). "The current data provide evidence that tumor STK11/LKB1 loss of function is a driver of CC, simultaneously serving as a genetic biomarker for this wasting syndrome." (PMID 37092555, 2023). "Of these 84 patients with cachexia, 20% of their tumors had a variant in STK11/LKB1." (PMID 37092555, 2023). "Finally, we are in parallel evaluating the secretomes of the CC-inducing tumors to determine if new soluble ligands are being created with loss of STK11/LKB1 function that act directly on adipose and/or muscle to promote cachexia." (PMID 37092555, 2023). "Whole-exome sequencing revealed that 8 of 10 cachexia lines, but none of the non-cachexia lines, possessed mutations in serine/threonine kinase 11 (STK11/LKB1), a regulator of nutrient sensor AMPK." (PMID 37092555, 2023).
cervical adenocarcinoma (6 papers, 2009 to 2026). An adenocarcinoma arising from the cervical epithelium.
cutaneous melanoma (6 papers, 2014 to 2025). A primary melanoma arising from atypical melanocytes in the skin. "While resistance mechanisms to immunotherapy in cutaneous melanoma have been uncovered, including alterations in JAK1/2, B2M, or STK11, a switch of oncogenic drivers under immunotherapy has not yet been observed." (PMID 34072863, 2021).
Fanconi anemia (6 papers, 2014 to 2022). Fanconi anemia (FA) is a hereditary DNA repair disorder characterized by progressive pancytopenia with bone marrow failure, variable congenital malformations and predisposition to develop hematological or solid tumors. "In addition, the top two enriched KEGG pathways were: 1) the Fanconi Anaemia pathway (represented by ATR, BRIP1, ERCC4, FANCC and POLH) and the FoxO signalling pathway (represented by CREBBP, NLK, PRKAA2, PRKAB1, PTEN and STK11)." (PMID 35768547, 2022).
hereditary cancer (6 papers, 2014 to 2024). Malignant neoplasms occurring in families at a rate greater than that expected by chance and caused by germline mutations in a specific gene. "Genetic susceptibility to hereditary cancers was assess–ed using targeted next-generation sequencing (NGS) and multiplex ligation-dependent probe amplification (MLPA) of the STK11 gene." (PMID 39115133, 2024).
hereditary cancer syndromes (6 papers, 2016 to 2025).
intestinal polyp (6 papers, 2003 to 2020). Discrete abnormal tissue masses that protrude into the lumen of the intestine. "Mice carrying one inactivated allele of Lkb1 (Stk11+/−) recapitulate PJS and die at 11 months after birth due to the development of intestinal polyps." (PMID 33236987, 2020). "Four of the patients in our study had extra-intestinal polyps: one of these harboured an LKB1/STK11 mutation and three did not." (PMID 12865922, 2003).
polyp (6 papers, 2012 to 2025). A usually exophytic mass attached to the underlying tissue by a broad base or a thin stalk. "Therefore, we speculated that these drastic immune and inflammatory responses promoted the EMT process and exacerbated polyp progression in paediatric patients with SJP and JPS, while intrinsic STK11/LKB1 mutation might induce EMT in PJS polyps." (PMID 38264936, 2024). "Studies have indicated that, compared to mutation-positive patients, those without STK11 mutations experience a median delay of 5.5 years in the age at first treatment (18.5 years vs. 13.0 years), along with a 47% reduction in the incidence of intussusception and a 30% decrease in polyp burden." (PMID 41195178, 2025).
sarcoma (6 papers, 2013 to 2025). A usually aggressive malignant neoplasm of the soft tissue or bone.
triple-negative breast carcinoma (6 papers, 2014 to 2024). An invasive breast carcinoma which is negative for expression of estrogen receptor (ER), progesterone receptor (PR), and human epidermal growth factor receptor 2 (HER2). "In one case report, a patient with triple-negative breast cancer with a point mutation in STK11 with loss of heterozygosity had a near-complete response with everolimus therapy." (PMID 32373524, 2020). "Whether in HR + or triple negative breast cancer, the frequency of copy number loss in STK11 was significantly higher in CMs." (PMID 38970069, 2024).
Hypertension (5 papers, 2014 to 2024). The presence of chronic increased pressure in the systemic arterial system. "As a result, to investigate the mechanism of the STK11 gene influencing the CAD morbidity, we assessed the association between the SNP rs12977689 and status of BMI, fasting plasma glucose, lipid profile, and the histories of hypertension." (PMID 28349069, 2017).
intestinal obstruction (4 papers, 2014 to 2023). Blockage of the normal flow of the intestinal contents within the bowel. "Patients with null STK11 mutations tend to have early-onset, frequent gastrointestinal symptoms including polyps, intussusception, and intestinal obstruction compared to patients with missense mutations." (PMID 36874343, 2023). "Our study similarly indicated that individuals with null mutations of STK11 had earlier onset for PJS symptoms, including intestinal obstruction and first operation events, than those with missense mutations." (PMID 32462036, 2020).